MMP2 (matrix metallopeptidase 2)
Diseases named in the same sentence as MMP2 in open-access papers (continued):
Sharing a sentence is not in itself a finding about the gene and the disease.
colorectal cancer (continued). "MiRNA29a promotes colorectal cancer cell metastasis via the down-regulation of KLF4 and e-cadherin, and up-regulation of MMP2." (PMID 37670299, 2023). "The present study revealed that MYL9 deletion downregulated the expression of MMP2 and MMP9 while MYL9 overexpression upregulated the expression of MMP2 and MMP9 in colorectal cancer cells." (PMID 34974798, 2022). "In colorectal cancer, miR-7 down-regulates the expression of paired box 6 (PAX6), which limits the PI3K/ERK-dependent up-regulation of MMP2 and MMP9 and hence inhibits colorectal cancer cell growth, proliferation, and metastasis." (PMID 36555120, 2022). "Previous evidence has indicated that MMP2 and MMP9 are two important genes that are closely related to the migration of tumor cells, including colorectal cancer." (PMID 34974798, 2022). "TANKs promote both MMP2/9 (matrix metalloproteinase 2/9) and TIMP (tissue inhibitors of metalloproteinase) through the activation of STAT3/STAT5 in colorectal cancer." (PMID 34202411, 2021). "Modulation and regulation of MMP2 and/or MMP9 activity by DDR1 have also been demonstrated in pituitary adenoma, colorectal cancer, and renal cancer (MMP2)." (PMID 33917302, 2021). "Some studies have found that Akt1 signaling significantly suppresses the expression of MMP2, MMP9, HIF1α, and VEGF in colorectal carcinoma cells." (PMID 34394377, 2021). "According to existing studies, MMP-2 and MMP-9 are overexpressed in colorectal cancer, and MMP-9 is a poor prognostic factor in preoperative CRT response of LARC patients." (PMID 32351671, 2020). "Upregulation of miR-9 produces downregulation of TM4SF1, MMP2, MMP9 and VEGF in colorectal carcinoma, inhibiting cell migration and invasion." (PMID 32000679, 2020). "Meanwhile, real-time qRT-PCR and western blot assays indicate that MnTE-2-PyP inhibits TGF-β-induced MMP-2 and MMP-9 in colorectal cancer cells." (PMID 30931081, 2019). "MnTE-2-PyP effectively suppressed TGF-β-induced cell migration and invasion and the expression of matrix metalloproteinase 2 (MMP-2) and matrix metalloproteinase 9 (MMP-9) in colorectal cancer cells." (PMID 30931081, 2019). "Excessive degradation of the matrix is one of the hallmarks of metastasis, and uPA, MMP-2, and MMP-9 play a role in human colorectal cancer progression, invasion, and metastasis." (PMID 31511625, 2019). "The expression of the gelatinases MMP-2 and MMP-9 is increased in colorectal cancer tissues when compared to concomitant normal tissues." (PMID 30931081, 2019). "Zhu and coworkers synthesized a matrix metalloproteinase-2 (MMP-2)-responsive nanocarrier for the co-delivery of camptothecin (CPT) and sorafenib, which was demonstrated to be an efficient approach for colorectal cancer synergistic therapy." (PMID 31754379, 2019). "The results pointed to FOXM1 facilitated the activities of MMP2 and MMP9 at least partly dependent on cell-surface HSPA in colorectal cancer cells." (PMID 27034162, 2016). "Immunostainings of 190 tumors resected from colorectal cancer patients indicated that PXN expression was positively correlated with Bcl-2, pBcl-2-S87, and MMP2 expression." (PMID 25826088, 2015). "The objective of the study was the assessment of serum levels and tissue expression of matrix metalloproteinase 2 (MMP-2) and tissue inhibitor of matrix metalloproteinases 2 (TIMP-2) in patients with colorectal cancer (CRC)." (PMID 24395652, 2014). "In conclusion, the aim of the present study was to assess the serum levels of MMP-2 and TIMP-2 as well as tumor tissue expression of these proteins in patients with colorectal cancer." (PMID 24395652, 2014). "The aim of the present study was to evaluate the relation of the genotype and phenotype of MMP-2 and MMP-9 in normal appearing mucosa with outcome of patients with colorectal cancer." (PMID 22472880, 2012). "We assessed MMP-2 and MMP-9 levels in normal colorectal mucosa from colorectal cancer patients in relation to the course of the disease." (PMID 22472880, 2012).
colorectal cancer (continued). "In the present study, we found high protein levels of MMP-2 and MMP-9 in mucosa adjacent to colorectal cancer tissue to be indicative for the course of disease, that is, independently associated with a worse survival of the patients." (PMID 22472880, 2012). "We studied the prognostic value of immunohistochemical expression of MMP-2, MMP-8, and MMP-9 in a series of 619 colorectal cancer patients using tissue microarray specimens." (PMID 23216739, 2012). "MMP-2 and MMP-9 levels in normal mucosa are indicative of the course of disease in colorectal cancer patients." (PMID 22472880, 2012). "In this study, we studied the prognostic value of MMP-2, MMP-8 and MMP-9 immunoexpression in colorectal cancer." (PMID 23216739, 2012). "Upregulation of MMP-2 and MMP-9 has been shown to play a key role in the progression, invasion, metastasis of colorectal cancer in animal models and patients." (PMID 21859479, 2011). "In the stage of cancer development, upregulation of MMP-2 and MMP-9 accelerates cell migration and invasion in colorectal cancer, thus resulting in the development of malignant tumor, poor prognosis, and shortening disease-free period and overall survival." (PMID 21859479, 2011). "Matrix metalloproteinase-2 (MMP-2), matrix metalloproteinase-9 (MMP-9), and urokinase-type plasminogen activator (uPA) are involved in colorectal cancer invasion and metastasis." (PMID 16916471, 2006). "The matrix metalloproteinases, MMP-2 and MMP-9, are capable of degrading components of the basement membrane, a vital barrier breached during the progression of colorectal cancer." (PMID 11401321, 2001). "Several pro-angiogenic (VEGF, Ang-2, PIGF, sVCAM-1, MCP-1, MMP-3, CHI3L1, IL-8 and CXCL16) and ECM-degrading (MMP-2 and MMP-7) proteins are known to be elevated after colorectal cancer resection, but in relation to postoperative complications such research remain scarce." (PMID 39167197, 2024). "The expression of MMP2 and MMP9 is related to the progression of colorectal cancer." (PMID 37492969, 2023). "Furthermore, by hampering miR-29a activity in repressing matrix metallopeptidase 2 (MMP2), APOBEC3G promotes colorectal cancer (CRC) liver metastasis." (PMID 33430133, 2021). "In addition, CCR1 knockdown significantly limits the activity and expression of matrix metalloproteinase-2 (MMP-2) and MMP-9, which predicts poor survival in colorectal cancer." (PMID 30979374, 2019). "Thyroid hormone induces expression of MMP-2 and MMP-9 in myeloma cells and colorectal cancer cells." (PMID 30915033, 2019). "In previous studies, we investigated the roles of MMPs including MMP2, MMP7, MMP8, MMP9 and MMP13 in the mice colorectal cancer model tissue, and observed that MMP7, MMP8, MMP9 are more important in colorectal cancer invasion and migration, and that MMP7 is regulated by NF-κB pathway." (PMID 31299935, 2019). "Also, it was found that TPS decreased the invading ability of the colorectal cancer cell line CT26, and the MMP-2 and MMP-9 protein expression levels were reduced by TPS treatment." (PMID 29419740, 2018). "Moreover, we observed statistically significant positive correlations between FOXM1 and MMP2 mRNA expression (n = 92, r = 0.6001, P = 2.71×10−10), between HSPA5 and MMP2 (n = 92, r = 0.403, P = 6.89×10−5) in colorectal cancer tissue specimens." (PMID 27034162, 2016). "Moreover, statistically significant positive correlations between FOXM1 and MMP2 mRNA expression, between HSPA5 and MMP2 were found in colorectal cancer tissue specimens." (PMID 27034162, 2016). "We also proved that B7-H3 was co-expressed with MMP2 and MMP9 in colorectal cancer patients." (PMID 27145365, 2016). "Moreover, the immunoreactivity of MMP-2 and TIMP-2 in colorectal cancer tissue correlated with the expression of these proteins in the interstitial inflammatory infiltrate cells as well as with the serum levels of TIMP-2 in CRC patients." (PMID 24395652, 2014).
colorectal cancer (continued). "Overexpressions of MMP-2 and MMP-9 have been demonstrated in human colorectal cancers." (PMID 23300633, 2012). "The correlation of high protein levels of MMP-2 and MMP-9 in mucosa adjacent to colorectal cancer tissue with worse survival, as we found, is probably also more, but not exclusively, related to endothelial cells in combination with epithelial cells and/or leukocytes." (PMID 22472880, 2012). "We hypothesised that the expression of MMP-2 and MMP-9 in normal mucosa of colorectal cancer patients could be relevant as well to the outcome in colorectal cancer." (PMID 22472880, 2012). "Different studies showed that some MMP, including MMP2, MMP7 and MMP9 are expressed in colorectal adenomas that are well established premalignant lesions of colorectal cancers, implying their role other than extracellular matrix destruction and metastasis in cancer development and progression." (PMID 17125518, 2006). "The aim of this study was to investigate whether immunohistochemical staining patterns of tissue inhibitor of metalloproteinases TIMP-2 and matrix metalloproteinases MMP-2 and MMP-9 can be predictors of tumour stage and survival time in colorectal cancer." (PMID 9310250, 1997). "However, MMP2 and MMP9 were significantly related to colorectal cancer and could be regulated by Chinese medicine." (PMID 34381520, 2021). "Taken together, these results verified that AAM effectively inhibits migration and VM formation by suppressing the ROS/HIF-1α/MMP2 pathway in colorectal cancer under hypoxic condition, suggesting AAM could serve as a therapeutic agent to inhibit VM formation in human colorectal cancer." (PMID 32499699, 2020). "A study showed that the expression of PCNA, Cyclin-D1, MMP-2, and MMP-9 genes can induce the formation of colorectal cancer and promote cancer cell proliferation, migration, and invasion, suggesting that these genes may be closely related to cell proliferation and migration." (PMID 32733959, 2020). "Furthermore, MMP-2 and MMP-9 are induced by TGF-β in SW480 colorectal cancer cells." (PMID 30931081, 2019). "Thus, we explored the potential role of MMP-2 and MMP-9 in TGF-β-mediated EMT in colorectal cancer." (PMID 30931081, 2019). "Our findings suggest that MMP-2 and TIMP-2 might play a role in the process of colorectal cancer invasion and metastasis, but the significance of their interactions with tumor stroma and interstitial inflammatory infiltration in colorectal neoplasia require further elucidation." (PMID 24395652, 2014). "We investigated whether the expression of membrane-type-1 matrix metalloproteinase (MT1-MMP), matrix metalloproteinase-2 (MMP-2) and tissue inhibitor of metalloproteinase-2 (TIMP-2) was consistent with the proposed roles of these proteins in promoting metastasis in colorectal cancer." (PMID 10901373, 2000). "Furthermore, the flavonoid abolished MMP-2 and MMP-9 activity in a concentration-dependent effect by suppressing pro-invasive Raf/PI3K signaling in murine colorectal carcinoma (CRC)." (PMID 37240168, 2023). "We did not confirm any significant correlation between MMP-2 and TIMP-2 expression in colorectal cancer cells or normal cells and tumor stage, tumor size (T), nodal involvement (N), presence of distant metastases (M), or resectability of tumor." (PMID 24395652, 2014). "The MMP-2 and MMP-9 protein levels in the colorectal cancer homogenates did not correlate with their respective SNP genotypes." (PMID 18506186, 2008). "However, according to the best of our knowledge, there is no study comparing serum levels of MMP-2 and TIMP-2 in colorectal cancer patients with their expression in colorectal tumor tissue: cancer cells, inflammatory infiltrate cells, and colorectal cells from adjacent normal tissue." (PMID 24395652, 2014).
bladder cancer (159 papers, 2004 to 2025). "MiR-146b, an oncogenic microRNA, has been implicated in various malignancies, including bladder cancer, where it promotes tumor progression by regulating genes involved in cell invasion and matrix remodeling, such as MMP2." (PMID 40224178, 2025). "The positive expression of MMP2 has been shown to be associated with advanced-stage retinoblastoma, oral cancers ovarian epithelial cancer, and bladder cancer." (PMID 38978899, 2024). "In bladder cancer, stromal cells including CAFs were shown to have high expression of various MMPs, especially MMP2, and the activation of MMP2 has been associated with TGF-β expression and activation of the p38 mitogen activated protein kinase (MAPK) pathway." (PMID 37569686, 2023). "Regarding bladder carcinoma, excretion of MMP-2 in urine has been associated with a high grade and high stage of the disease." (PMID 32751899, 2020). "And β-catenin has been reported to transcriptionally induced MMP2 expression which has been associated with induction of bladder cancer invasiveness." (PMID 27058893, 2016). "MMP2 is associated with bladder cancer invasiveness and its expression is often used to measure the migration ability of tumor cells." (PMID 24223658, 2013). "MMP2 is a statistically significant marker in blood plasma for bladder cancer detection with an increased diagnostic value in combination with MMP9 and TIMP1." (PMID 16901349, 2006). "Moreover, it seems that MMP-9 has higher clinical utility than MMP-2 as a potential therapeutic option and a diagnostic biomarker of urinary bladder cancer." (PMID 36979935, 2023). "Importantly, this includes cleavage sites for the metalloproteases MMP-2, -3, -12, and -13, with several MMPs elevated in bladder cancer and associated with increased stage." (PMID 33718196, 2021). "Besides, there are seven included studies reported the association between MMP2 and bladder cancer, and six investigations focused on MMP9." (PMID 28427222, 2017). "The results indicate that potentially functional MMP-1-1607 1G/2G and MMP-2-1306 C/T polymorphisms may play an important role in the development of bladder cancer." (PMID 24390660, 2014). "Expression of MMP2 is associated with bladder carcinoma cell invasion and metastasis." (PMID 21143984, 2010). "But for the first time we could evaluate that MMP2 as a statistically significant marker in blood plasma for bladder cancer detection with an increased diagnostic value in combination with MMP9 and TIMP1." (PMID 16901349, 2006). "The MMPs with the highest correlation with GHR expression in both female and male patients with bladder cancer were MMP2 (rho = 0.472 (F), 0.457 (M)), MMP16 (rho = 0.464 (F), 0.509 (M)), and MMP23B (rho = 0.316 (F), 0.452 (M))." (PMID 40806252, 2025). "The findings of our present study suggest that XIAP and YTHDC1 interact to regulate the stability of MMP-2 mRNA and promote metastasis of bladder cancer." (PMID 40133252, 2025). "As a matrix metalloproteinase, MMP-2 degrades the extracellular matrix, thereby increasing the invasive capacity of bladder cancer cells." (PMID 41179679, 2025). "Urinary concentration of MMP2 is a promising biomarker of bladder cancer and allows discrimination between BC patients and healthy subjects; however, it failed in accurate BC identification in the early stages of the disease." (PMID 41228251, 2025). "The ability of MMP2 to degrade collagens is significant in the case of bladder cancer, because collagens are among the main components of the urinary bladder." (PMID 41228251, 2025). "Collectively, these findings demonstrate that XIAP is a critical regulator of YTHDC1 and pinpoint the XIAP/YTHDC1/MMP-2 axis as a promising target for the treatment of bladder cancer." (PMID 40133252, 2025). "In a previous study, we found that MMP-2 is an important molecular marker of metastasis of bladder cancer." (PMID 40133252, 2025).
bladder cancer (continued). "These experiments revealed that XIAP promotes ubiquitination of YTHDC1, positively regulating expression of the MMP-2 and promoting metastasis of bladder cancer." (PMID 40133252, 2025). "Within the pathways associated with glyphosate-induced kidney injury, the bladder cancer pathway exhibits the lowest p-value, highlighting genes such as MMP9, MMP2, and SRC." (PMID 40851020, 2025). "We have published studies demonstrating that XIAP promotes metastasis of bladder cancer by regulating MMP-2 mRNA." (PMID 40133252, 2025). "In bladder cancer, loss of GATA3 can induce EMT and the expression of pro-metastatic molecules, such as MMP-2 and MMP-9, leading to disease progression." (PMID 39781348, 2025). "MMP2 was determined in blood plasma or in cancer cell culture using the ELISA kit and in bladder cancer tissue by means of gelatine zymography." (PMID 41228251, 2025). "The participation of MMP2 in various pathways related to bladder cancer has been reported in a range of papers." (PMID 41228251, 2025). "This study evaluated the effects of cisplatin, gemcitabine, and the APC/C inhibitor proTAME, both individually and in combination, on cell migration and MMP2/MMP9 expression in RT4 bladder cancer and ARPE-19 normal epithelial cells." (PMID 40136519, 2025). "The MMP2 protein promotes extracellular matrix degradation, thereby enhancing bladder cancer cell invasion and metastasis and contributing to disease progression." (PMID 41179679, 2025). "After transient knockdown of the SHMT2 gene expression, Western Blot was performed to detect changes in invasion-related genes E-cadherin, N-cadherin, and MMP2 in bladder cancer cells T24 and J82." (PMID 38594513, 2024). "In this study, the bladder cancer tissues were examined to demonstrate the presence and activity of two gelatinases, MMP-2 and MMP-9." (PMID 36979935, 2023). "In human bladder cancer cells, suppression of MMP-2, MMP-9 and IL-6 expression, as well as induction of mesenchymal-to-epithelial transition (MET were found in the presence of DEX." (PMID 36980530, 2023). "The expression and activity of MMP-2 is increased in bladder cancer urothelial cells compared to normal tissues." (PMID 37932474, 2023). "The CXCL5/CXCL2 axis also promotes bladder cancer cell migration by upregulating MMP2/MMP9, which is an Akt-dependent pathway." (PMID 37373052, 2023). "For example, the STAT3 pathway regulates the proliferation and migration of drug-resistant bladder cancer cells by regulating Cyclin D1 and MMP2." (PMID 36793374, 2023). "It has been proven that the activity of MMP-2 in bladder cancer is markedly elevated in comparison with the healthy tissue." (PMID 36979935, 2023). "Collectively, these findings suggest that SFN suppresses bladder cancer metastasis via the COX-2/MMP2, MMP9/ZEB1, and Snail pathway as well as the miR-200c/ZEB1 pathway." (PMID 37627900, 2023). "Peng et al35 reported that PHLPP2 inhibited bladder cancer invasion by promoting the degradation of matrix metalloproteinase 2 (MMP2) via p62-mediated autophagy." (PMID 37737218, 2023). "The downregulation of NANOG decreased bladder cancer cell migration and invasion as well as MMP2 and MMP9 mRNA levels." (PMID 37627900, 2023). "Up-regulated miR-494 destabilizes c-Myc mRNA and inhibits its translation, ultimately suppressing c-Myc-dependent matrix metalloproteinase (MMP)-2 expression, i.e., inhibiting bladder cancer proliferation and invasion via the HuR/JunB/miR-494/c-Myc/MMP-2 axis." (PMID 36831493, 2023). "A similar amount of MMP-9 was found in LG cancer and a more than two times higher amount was found in HG urinary bladder cancer in comparison with the MMP-2 content." (PMID 36979935, 2023). "Considering the blood test results, healthy patients represented a similar MMP-2 concentration in comparison with patients with urinary bladder cancer." (PMID 36979935, 2023).